LEP (leptin)
Diseases named in the same sentence as LEP in open-access papers (continued):
Sharing a sentence is not in itself a finding about the gene and the disease.
diabetes (continued). "However, data regarding the associations of leptin and sOB-R and MetS, the important risk factor of diabetes and CVD, is rather limited and inconsistent." (PMID 21347230, 2011). "In the Sandy Lake Health and Diabetes Project, leptin, CRP, IL-6 and serum amyloid A were included in a risk model based on cardiometabolic risk factors, adiponectin and impaired glucose tolerance, but could not improve diabetes prediction." (PMID 21674000, 2011). "Similarly, lipodystrophic syndromes, with complete or partial absence of subcutaneous adipose tissue, have been associated with low leptin concentrations and diabetes." (PMID 21760816, 2011). "On the other hand, a decrease of leptin levels associated with the reduction of body mass has been implicated in the pathogenesis of insulin-deficient diabetes, in which leptin replacement improved insulin sensitivity and decreased hepatic triglyceride content." (PMID 20953376, 2010). "In “case-mix + laboratory”-adjusted logistic regression analyses, we observed that female sex, diabetes, presence of an arteriovenous fistula/graft, and lower serum albumin, IL-6, and adiponectin levels were significantly associated with the highest tertile of leptin." (PMID 41295840, 2025). "Indeed, reinforcing this notion, a recent meta-analysis involving ten randomized controlled trials highlighted that the use of SGLT2i in individuals with type 2 diabetes mellitus was linked to reductions in circulating leptin levels and increases in adiponectin levels." (PMID 37834783, 2023). "In particular, leptin-deficient mice (ob/ob) and leptin-receptor-deficient mice (db/db), characterized by mutations of the genes encoding leptin or its receptor, cause alterations in leptin-dependent pathways with the subsequent development of severe Ob and diabetes." (PMID 37298291, 2023). "However, an extensive study with a larger sample size should be used to identify the real implication of correlations between the LEP polymorphism and diabetes mellitus, strengthening evidence for the LEP polymorphism as a genetic factor in diabetes mellitus risk." (PMID 35334523, 2022). "Leptin replacement therapy has been used successfully in humans to treat congenital leptin deficiency and generalized lipodystrophy, and it has also been investigated as a potential treatment for hypothalamic amenorrhea, other forms of lipodystrophy, and diabetes." (PMID 34299256, 2021). "On the other hand, leptin might be used as an adjunct to insulin therapy in patients with insulin-deficient diabetes, providing insight into its therapeutic properties as an antidiabetic agent; moreover, leptin monotherapy has been reported to reverse type 1 diabetes independent of insulin." (PMID 33167521, 2020). "Thus, attenuation or restoration of Lepr in adipocytes alters the plasma insulin profile following glucose ingestion, modifies the glucose-lowering effect of prolonged leptin therapy in insulin-deficient diabetes, and may modulate weight gain." (PMID 30824713, 2019). "Loci for randomized variance in plasma leptin is in line with the notion of periodic or episodic variation in satiety, and the linkage of several leptin dispersion loci to diabetes susceptibility loci suggests a role for physiological randomization in diabetes physiology with insulitis itself." (PMID 31661517, 2019). "Some studies have suggested that reduced leptin levels in insulin-deficient diabetes may activate the hypothalamic-pituitary-adrenal (HPA) axis and that restoration of plasma leptin may attenuate hyperglycemia in large part by suppression of the HPA axis and reducing secretion of glucocorticoids." (PMID 29190687, 2017). "Thus, our results highlight that inhibition of alpha cell glucagon production is one potential mechanism by which leptin might be effective in controlling hyperglycemia in individuals with diabetes caused by diminished insulin reserve." (PMID 28702245, 2016).
diabetes (continued). "In acute stroke among patients with diabetes, lower leptin has paradoxically correlated with worse outcomes, potentially reflecting catabolic states." (PMID 41567175, 2026). "PTP 1B is a member of a class of intracellular enzymes that negatively regulate the leptin signaling system and insulin receptors, for this reason, they are more involved in diabetes control." (PMID 39940428, 2025). "This study aimed to evaluate the effects of pre-conditioning exercise on body lipid metabolism, leptin secretion, and the downstream pathways at the early stage of type 2 diabetes mellitus (T2DM)." (PMID 39877628, 2025). "Leptin acted as a diabetes-specific regulator of mitochondrial crosstalk, whereas ADIPOQ served that role in relation to sarcopenia, pointing to disease-tailored endocrine wiring." (PMID 40869253, 2025). "In the cancer group, diabetes was more prevalent, which would imply that higher leptin levels should be expected." (PMID 40940878, 2025). "It is suggested that subcutaneous leptin therapy is beneficial in some severe lipodystrophy in monogeneic-resistant diabetes." (PMID 40149950, 2025). "Cluster 1 scores were positively associated with peak VO2 and C[a‐v]O2 and negatively associated with age and resistin (p < 0.01 for all), with weaker correlations with diabetes and leptin." (PMID 41351269, 2025). "The study examine the profiles of blood leptin, lipids, HbA1C, and renal function in type 2 diabetes mellitus patients, with a particular emphasis on differences between non-obese and obese patients." (PMID 41239622, 2025). "As OB mice are leptin-deficient, we propose a leptin-independent mechanism of STAT3 activation, which is mediated via macrophages in this diabetes-resistant mouse strain." (PMID 39508880, 2025). "Several molecules, including adrenomedullin, adipokines (including lipocalin, leptin, and adiponectin), and calprotectin, have been reported to be associated with PDAC‐associated diabetes mellitus." (PMID 40351037, 2025). "The two studies employed genetically modified mice: db/db mice and ob/ob mice respectively, both commonly used animal models in diabetes research based on leptin or leptin receptor gene modifications." (PMID 40386230, 2025). "Selective breeding has also produced Zucker Diabetic Sprague–Dawley rats, which develop diabetes slowly, better mimicking human type II diabetes while retaining functional leptin signaling." (PMID 41030912, 2025). "The divergence of LEP (diabetes-specific) versus AdipoQ (sarcopenia-specific) further emphasizes distinct endocrine wiring that tailors adipokine–mitochondria crosstalk to each disease’s metabolic context." (PMID 40869253, 2025). "Leptin resistance, common in obese or type 2 diabetes mellitus patients, is characterized by a reduced tissue response to leptin." (PMID 40729334, 2025). "Sleep deprivation can lead to impaired glucose tolerance, elevated evening cortisol levels, heightened sympathetic nervous system activity, and reduced leptin secretion, potentially contributing to diabetes, hypertension, and obesity." (PMID 40819005, 2025). "In individuals with OSA and diabetes, adiponectin and omentin-1 levels are often decreased, while leptin, resistin, and chemerin levels are typically increased." (PMID 41155523, 2025). "A significant increase in leptin levels was observed in the groups of participants with diabetes and healthy participants after consuming a veggie burger compared to a conventional one." (PMID 39125378, 2024). "Both bioLep and total leptin were lower after the Paleolithic diet compared to after the diabetes diet." (PMID 39232748, 2024). "Leptin is an important adipose tissue-derived hormone that is involved in the pathophysiological mechanisms of diabetes." (PMID 38243194, 2024).
diabetes (continued). "After adjustment for leptin, hypertension and diabetes separately, we observed the largest attenuation of the association between BMI, TBF and moderately increased albuminuria after adjustment for hypertension and diabetes compared with adjustment for leptin." (PMID 38627329, 2024). "Normoglycemic South Asian women had similar concentrations of hsCRP, IL-6, leptin and adiponectin as women with prediabetes or diabetes." (PMID 39097697, 2024). "It has been shown that circulating leptin concentration was significantly higher in women with heart failure or diabetes than men." (PMID 38686200, 2024). "Based on empirical evidence, among the adipokines discovered thus far, adiponectin, leptin, resistin, and apelin emerge as the most promising candidates for clinical application, particularly in the realms of myocardial protection and diabetes management." (PMID 39538244, 2024). "This study aims to investigate the relationship between circulating levels of adiponectin and leptin and the risk of developing DPN in individuals with diabetes." (PMID 39735639, 2024). "What’s more, researchers suggested that targeting cannabinoid (CB) receptors/modulating the degree or activity of endocannabinoids in tissue is beneficial to decrease insulin/leptin resistance in diabetes and mitigate the myocardial damage during I/R phase." (PMID 39538244, 2024). "PHE significantly improved the diabetes state in a dose-dependent way by decreasing leptin and increasing GCK, most likely via reducing ROS generation and inflammatory molecules like IL-6 and TNF-α." (PMID 38234664, 2024). "The model for leptin included as independent predictors age, gender, leptin levels, diagnosis, BMI, diabetes, dyslipidaemia, hypertension, smoke and atrial fibrillation." (PMID 38686200, 2024). "The Paleolithic diet resulted in higher satiety, a more beneficial lipid profile, lower body weight, waist circumference, HbA1c and total leptin levels compared to the diabetes diet." (PMID 39232748, 2024). "This meta-analysis demonstrated that the consumption of L-carnitine at doses exceeding 3 g/day for a duration of less than 12 weeks exhibits a significant impact on leptin levels in individuals with diabetes." (PMID 39085907, 2024). "Leptin—a 16 kDa adipokine, composed of 167 amino acids, considered an adipocyte-derived satiety hormone—is elevated during pregnancy, and significantly higher in pregnant women with diabetes mellitus, suggesting leptin resistance." (PMID 39683415, 2024). "The analysis indicated that total leptin in blood was significantly increased in individuals with diabetes, compared to controls (SMD 0.55; 95% CI 0.34–0.77; p < 0.0001)." (PMID 39684379, 2024). "Research indicates that metformin therapy, by reducing pericoronary fat levels, contributes to improved cardiovascular outcomes through the diminution of inflammatory markers, SGLT2, and leptin levels in individuals with pre-diabetes." (PMID 39538244, 2024). "Lipid NPs deliver siRNA of glucagon receptors in a mouse model of diabetes and show better results than leptin in reducing blood sugar levels in diabetes." (PMID 38421835, 2024). "We found many previously reported associations, such as associations between leptin and sex and CRP and BMI, and also new associations that are biologically plausible, such as LIPL and LIPE with diabetes status." (PMID 38307861, 2024). "Considering the complex and multiple functions of OT, such as the lipolytic effect in adipose tissues, we also adjusted the OT statistical analysis based on the leptin level, BMI and diabetes." (PMID 37298701, 2023). "The observed alterations significantly correlated with plasma leptin levels and diabetes status as crucial amplifying factors." (PMID 36921085, 2023). "Adverse leptin and adiponectin production reflecting dysfunctional adipose tissue is presented in diabetes." (PMID 37444627, 2023).
diabetes (continued). "In summary, leptin replacement in rat models of poorly controlled diabetes reduces lipolysis, liver glucose production, and hyperglycemia." (PMID 38260129, 2023). "The adiponectin/leptin ratio was proposed as a functional marker of fat inflammation in human patients of diabetes." (PMID 36935456, 2023). "Whereas, the observed inverse association between diabetes and prostate cancer can be explained by the lower levels of testosterone or leptin and insulin-like growth factor 1 in men with diabetes." (PMID 37900125, 2023). "Recent studies have found that compared to individuals with systemic health, the adiponectin level in periodontitis patients with diabetes is significantly lower and the leptin level is significantly higher." (PMID 37664859, 2023). "Adiponectin, leptin, visfatin, and chemerin play an important role in the occurrence, development, and diabetes-related complications of T2DM." (PMID 37664859, 2023). "Here, we utilized the UCD-T2DM rats which possess the polygenic adult onset of diabetes with preserved leptin signaling." (PMID 37189747, 2023). "to study the relationships of leptin and leptin SR with adiposity indices, and glycemic indices in patients with type 2 diabetes mellitus (T2DM) compared to healthy subjects." (PMID 36950695, 2023). "Buettner proposed “leptin therapy” as a superior alternative to insulin for the management of type 1 diabetes mellitus." (PMID 37241229, 2023). "Among children of normal weight, leptin levels were significantly different between healthy children and children with newly diagnosed diabetes, as well as participants from the DM1w group." (PMID 37670877, 2023). "This adipokine can also improve the diabetes of lipodystrophic mice independently of insulin, suggesting that leptin has therapeutic potential for the treatment of T1DM." (PMID 36674935, 2023). "Leptin-deficient BALB/cJ mice have a higher reduction in body weight and adiposity than leptin-deficient C57BL/6J mice, but they developed severe diabetes." (PMID 37600780, 2023). "Among children with newly diagnosed diabetes, leptin levels were significantly different between underweight, overweight, and obese children (p<0.001)." (PMID 37670877, 2023). "Nikmah and Dany showed that the leptin levels of individuals with diabetes were higher than normal subjects." (PMID 37175192, 2023). "The purpose of our study was tomeasure the level of leptin and biologically active leptin (bioLEP) in children with type 1 diabetes, depending on the duration of diabetes and its degree of metabolic control." (PMID 37670877, 2023). "Insulin treatment increases leptin levels (5.18 ± 5.48 ng/ml) in children with newly diagnosed diabetes, which is consistent with our results." (PMID 37670877, 2023). "Logistic regression models were used to estimate the associations between OT levels and KL progression while controlling for gender, age, BMI, diabetes and leptin levels." (PMID 37298701, 2023). "They secrete various adipokines, including interlukin-6 and leptin, which are involved in the development of diabetes and metabolic disorders." (PMID 37064684, 2023). "Generalized linear model with leptin or insulin as the dependent variable, maternal diabetes as a factor and maternal BMI or birth weight as potential covariates." (PMID 35197933, 2022). "The current study aimed to investigate the relationship between leptin and resistin levels with novel refined subgroups in patients with type 2 diabetes mellitus (T2DM)." (PMID 34996484, 2022). "The recognized role of leptin in mediating the fibroblastic and inflammatory processes as well as the known diabetes-leptin/diabetes-SS linkages inspired us to investigate the role of leptin in the pathogenesis of SS." (PMID 36295022, 2022). "One plausible explanation for this is that diabetes attenuates the neuroprotective effects of leptin by increasing leptin resistance." (PMID 36097042, 2022).
diabetes (continued). "There is also a large amount of synergy and antagonism between hormones, such as the synergistic effect between leptin and insulin and the treatment of diabetes by melatonin osteogenic differentiation inhibition." (PMID 36188222, 2022). "The results demonstrate that birth weight is the strongest predictor of cord blood leptin, with maternal BMI and diabetes having a greater influence on insulin than leptin." (PMID 35197933, 2022). "We compared leptin and IL-6 level across two common perinatal conditions that are coupled with inflammation, diabetes and chorioamnionitis." (PMID 35197933, 2022). "Db/db mice are obese, highly insulin - and leptin-resistant and spontaneously and progressively develop worsening diabetes over time culminating in beta cell mass depletion." (PMID 36992750, 2022). "For instance, at birth leptin appears to be strongly influenced by maternal weight and BMI before pregnancy, as well as by other maternal variables during gestation such as diabetes, smoking, and level of physical activity." (PMID 36064746, 2022). "In the current study, injection of STZ increased blood glucose, dysregulated lipid profile, decreased the amount of insulin and leptin, and developed diabetes." (PMID 36479221, 2022). "There was a significant difference in the genotypic model and allelic frequencies of LEP promoter gene (G2548A) polymorphism between T2DM and non-diabetes subjects (P > 0.05)." (PMID 36381191, 2022). "Leptin exerts its function by binding to the leptin receptor (Ob-R), a product of the diabetes (db) gene." (PMID 36551211, 2022). "By multivariate regression, birth weight was the strongest predictor of cord blood leptin (P<0.001), while maternal diabetes and BMI were the strongest predictors of cord blood insulin (both P<0.001)." (PMID 35197933, 2022). "The goal of this study was to evaluate the differential impact of growth, maternal diabetes, and chorioamnionitis on umbilical cord blood leptin and IL-6 levels." (PMID 35197933, 2022). "Physical activity leads to reduced inflammatory pathways that improve the development of insulin and leptin resistance, abdominal obesity, atherosclerosis, neurodegeneration, Type 2 diabetes mellitus, dementia, and cardiovascular disease." (PMID 35743182, 2022). "This suggests that the neuroprotective effect of leptin, which increases with increasing body weight, decreases in individuals with diabetes." (PMID 36097042, 2022). "In this article we discuss the most important topics and the relationship of leptin to immunity, cortisone, and diabetes, in addition to pregnancy, tumors, and others." (PMID 35027962, 2021). "Our results confirm that there is a high correlation between leptin, TNF-α, and insulin and these correlations cause many disorders in people with diabetes." (PMID 34039404, 2021). "In the multivariate analysis, for the leptin/ghrelin ratio, patients ‘gender, diabetes, and body mass index were independent factors." (PMID 34829886, 2021). "This led us to postulate that treating diabetic animals with leptin would ameliorate many of the diabetes-induced central and neuroendocrine dysfunction." (PMID 34947993, 2021). "While studies assessing the correlation between leptin and diabetes mellitus are sparse, a predictive role of circulating serum leptin on reducing insulin sensitivity over time was observed in nondiabetic men." (PMID 34299261, 2021). "The eldest female had type 2 diabetes mellitus, which was controlled during the course of leptin replacement." (PMID 34504472, 2021). "The leptin/ghrelin ratio correlated with BMI (r = 0.304, p = 0.018), ponderal status (r = 0.29, p = 0.021), diabetes presence (r = 0.318, p = 0.013), insulin (r = 0.287, p = 0.026), and patients’ sex (r = −0.404, p = 0.001)." (PMID 34829886, 2021). "Diabetes-related plasma biomarkers insulin, leptin, resistin, and glucagon were significantly reduced by quercetin supplementation." (PMID 34439499, 2021).